SEMA3C (semaphorin 3C)
Diseases named in the same sentence as SEMA3C in open-access papers (continued):
Sharing a sentence is not in itself a finding about the gene and the disease.
breast carcinoma (21 papers, 2014 to 2024). "SEMA3C expression was also significantly lower in ER-positive tumours compared to ER-negative tumours, further supporting the positive association between SEMA3C and aggressive breast cancer biology." (PMID 37685898, 2023). "To further explore the molecular mechanisms underlying SEMA3C’s role in breast cancer, we conducted in vitro cell-based experiments." (PMID 37443749, 2023). "The expression of SEMA3C is related to tumor progression, and it has been reported that SEMA3C is directly associated with the poor prognosis of lung cancer, breast cancer, gastric cancer, and ovarian cancer." (PMID 35437508, 2022). "Recent studies have shown that SEMA3C plays an oncogenic role and associated with poor prognosis and progression in multiple cancer types, including breast cancer." (PMID 32241267, 2020). "To assess the clinical relevance of SEMA3C in ER+ breast cancer, we analyzed publicly available clinical datasets to investigate the association between SEMA3C expression and patient characteristics, as well as the correlation of SEMA3C with known breast-cancer-associated genes." (PMID 37443749, 2023). "Increased levels of SEMA3C transcripts were observed in poorly differentiated or advanced breast cancers and in patients who developed local recurrences." (PMID 37685898, 2023). "Previously, we have shown that Semaphorin 3C (SEMA3C) is an autocrine growth factor that drives the growth and treatment resistance of various cancers, but its role in breast cancer progression and endocrine resistance is poorly understood." (PMID 37443749, 2023). "We found SEMA3C’s mRNA expression to be the highest in ER+/HER2− breast cancer patients when compared to all other subtypes, including HER2+ and Triple-Negative breast cancer (p < 0.0001)." (PMID 37443749, 2023). "Here, we examined the role of SEMA3C in the context of ER+ breast cancer, with the aim of defining SEMA3C as a novel potential therapeutic target for this breast cancer subtype." (PMID 37443749, 2023). "This study provided novel insights into the biology of ER+ breast cancer, highlighting the potential role of SEMA3C in driving tumor progression and maintaining tumor cell proliferation, especially in the context of endocrine resistance." (PMID 37443749, 2023). "Treatment with B1SP Fc fusion protein, a SEMA3C pathway inhibitor, attenuated SEMA3C-induced signaling and growth across a panel of tamoxifen sensitive and resistant ER+ breast cancer cells." (PMID 37443749, 2023). "Next, we investigated SEMA3C mRNA expression in 1764 breast cancer patients using clinical data from a METABRIC study on cbioportal (see Methods for details on the sample grouping in each dataset)." (PMID 37443749, 2023). "The expression of SEMA3C is related to tumor progression and poor prognosis in lung cancer, prostate, breast cancer, gastric cancer and ovarian cancer, which makes it a potential therapeutic target for malignant diseases." (PMID 37893159, 2023). "This study highlights the therapeutic potential of targeting SEMA3C in the treatment of ER+ breast cancer, with particular relevance for hormone-resistant cases." (PMID 37443749, 2023). "Our findings on the role of SEMA3C in ER+ breast cancer have potential implications for breast cancer research and treatment." (PMID 37443749, 2023). "To assess its drugability potential within ER+ breast cancer, we conducted proof-of-concept testing using B1SP, a novel SEMA3C pathway inhibitor, to lay the groundwork for the development of SEMA3C-targeted therapies in ER+ breast cancer." (PMID 37443749, 2023). "This study demonstrates that SEMA3C is an ER-induced autocrine growth factor that drives the signaling and growth of ER+ breast cancer, mainly by activating MAPK and AKT pathways." (PMID 37443749, 2023).
breast carcinoma (continued). "Our observation of higher SEMA3C expression in breast cancer cell lines corroborates the clinical observation made earlier, in which the transcript levels of SEMA3C were higher in breast cancer tissues as compared to adjacent normal mammary tissues." (PMID 37443749, 2023). "Among all breast cancer subtypes, ER+ breast cancer expresses the highest levels of SEMA3C transcripts." (PMID 37443749, 2023). "In breast cancer, SEMA3C silencing has been shown to inhibit the cell invasion of MCF7 and MDA-MB-231 cells." (PMID 37443749, 2023). "Our study indicates that SEMA3C is a potential therapeutic target in ER+ breast cancer, as it drives the activation of RTK signaling pathways, and SEMA3C knockdown significantly impacts cell growth." (PMID 37443749, 2023). "Here, we show that SEMA3C is significantly upregulated in ER+ breast cancer patients and cell lines, and its expression is modulated by the estrogen receptor." (PMID 37443749, 2023). "Our findings validate previous research showing that SEMA3C knockdown inhibits the proliferation of ER+ breast cancer cells, and extends these insights by demonstrating that SEMA3C is an autocrine growth factor that stimulates the growth of ER+ cell lines." (PMID 37443749, 2023). "We confirmed that both MCF7 and T47D cells express high levels of Plexin B1, and established that Plexin-B1 serves as the receptor for SEMA3C in ER+ breast cancer cells." (PMID 37443749, 2023). "SEMA3C is highly expressed in aggressive, highly metastatic Her2-positive breast cancer and SEMA3C depletion reduced cell migration." (PMID 35785187, 2022). "SEMA3C is overexpressed in gastric, breast, and liver cancers, and its expression level is correlated with the stage and grade of gastric and breast cancers." (PMID 36277723, 2022). "We have also observed epigenetic upregulations of SULF1 and SEMA3C earlier found upregulated in gastric cancer and breast cancer, respectively." (PMID 31796082, 2019). "Sema3C is expressed more highly in triple-negative and Her2-positive breast cancer, two aggressive subtypes that are highly metastatic." (PMID 29642487, 2018). "In breast cancer, Sema3C expression correlates with increased microvessel density, but in oral cancer, Sema3C levels inversely correlates with microvessel density." (PMID 29642487, 2018). "SEMA3C also plays a critical role in the activation of phospho-EGFR levels, a key player in endocrine resistance of ER+ breast cancer cells, suggesting that targeting SEMA3C could be effective in overcoming endocrine resistance." (PMID 37443749, 2023). "After exploring cell signaling pathways activated by SEMA3C, we wanted to understand whether ER+ breast cancer cells were dependent on SEMA3C-induced signaling." (PMID 37443749, 2023). "First, we investigated the levels of SEMA3C protein in a panel of breast cancer cell lines." (PMID 37443749, 2023). "However, the mechanism by which SEMA3C drives breast cancer progression and endocrine resistance is poorly understood." (PMID 37443749, 2023). "Targeting SEMA3C could be a potential strategy for combating ER+ breast cancer, highlighting its potential as a therapeutic target in precision oncology." (PMID 37443749, 2023). "This provides further evidence that SEMA3C inhibition could be a well-tolerated and relatively safe option for breast cancer patients and should be further explored in clinical trials as a potential therapeutic approach." (PMID 37443749, 2023). "Consistent with our clinical observations, we found that SEMA3C protein expression is significantly elevated in ER+ breast cancer cell lines, MCF7 and T47D, as compared to MCF10A, which are immortalized non-malignant breast epithelial cells that possess many characteristics of normal breast cells." (PMID 37443749, 2023). "Notably, among the various subtypes of breast cancer, ER+ breast cancer exhibited the highest expression of SEMA3C mRNA in clinical samples." (PMID 37443749, 2023).
breast carcinoma (continued). "Furthermore, our study revealed that SEMA3C protein levels were significantly higher in ER+ breast cancer cell lines MCF7 and T47D compared to the immortalized normal epithelial cell line MCF10A." (PMID 37443749, 2023). "Our data further indicated that SEMA3C functions as an ER-induced growth factor that activates and maintains sustained proliferative and survival signaling pathways in both tamoxifen-sensitive and -resistant ER+ breast cancer cells." (PMID 37443749, 2023). "Combination therapies have emerged as a powerful approach for combating breast cancer, and our study suggests that targeting SEMA3C in combination with endocrine therapy could be a highly effective strategy." (PMID 37443749, 2023). "Here, our study implicates SEMA3C in a functional role in ER+ breast cancer signaling and growth that suggests ER+ BCa patients may benefit from SEMA3C-targeted therapy." (PMID 37443749, 2023). "We further identified ER as a key transcriptional regulator of SEMA3C expression in ER+ breast cancer cells, establishing SEMA3C as a tumor vulnerability in ER+ breast cancer and providing a mechanistic link between the SEMA3C-ER pathway and growth signaling in ER+ breast cancer." (PMID 37443749, 2023). "This might suggest, in some ER+ breast cancer cases, that the consistent activation of SEMA3C is exploited by the tumor cell population to evade treatment efficacy." (PMID 37443749, 2023). "Additionally, further studies with larger sample sizes are needed to confirm our findings and to explore the potential of SEMA3C as a biomarker and therapeutic target for ER+ breast cancer." (PMID 37443749, 2023). "We further demonstrate the druggable potential of SEMA3C by using the B1SP Fc fusion protein, a SEMA3C pathway inhibitor that has displayed inhibitory effects on the growth and signaling of ER+ breast cancer cells comparable with those observed during SEMA3C silencing." (PMID 37443749, 2023). "Regarding the function of SEMA3C in breast cancer, our study showed SEMA3C was down-regulated in primary tumours with further reduced expression in the aggressive subtype Her2 and basal-like tumours, indicating a tumour suppressor role of SEMA3C in breast cancer." (PMID 32241267, 2020). "Silencing SEMA3C represses breast cancer cell migration and proliferation." (PMID 33396906, 2020). "Therefore, the role of SEMA3C either functioning as a tumour promoter or suppresser in breast cancer still needs to be validated in future studies." (PMID 32241267, 2020). "In breast cancer cell lines, Sema3C depletion reduces cell proliferation and migration." (PMID 29642487, 2018). "In breast cancer, Sema3C appears to promote tumor progression." (PMID 29642487, 2018). "In line with this, Sema3C has been reported to promote survival and tumorigenicity of glioma stem cells in an autocrine/paracrine manner, and to enhance adhesion, migration and invasion of breast cancer cells." (PMID 29141914, 2018). "Activation of alternate SEMA3C‐driven RTKs may confer escape mechanisms for acquired resistance to RTK inhibitors such as ErbB2 amplification in breast cancer and MET amplification in colon and lung cancer." (PMID 29348142, 2018). "Based on our previous report, which suggested that SEMA3C transactivates multiple RTKs through its interaction with Plexin B1, we conducted plexin B1 silencing experiments to investigate whether SEMA3C drives signaling through Plexin B1 in ER+ breast cancer." (PMID 37443749, 2023). "Moreover, the study’s findings could pave the way for the development of new and more effective SEMA3C inhibitors with fewer off-target effects and less toxicity, leading to improved outcomes for breast cancer patients." (PMID 37443749, 2023). "Several studies showed that increased expression of Sema3C is a poor prognostic factor for patients with breast cancer, glioblastoma, or gastric cancer, implying that Sema3C may be involved in cancer progression possibly through the stimulation of angiogenesis." (PMID 30304095, 2018).
breast carcinoma (continued). "To this end, we conducted a siRNA knockdown of SEMA3C (25 nM) on MCF7 and T47D cells, and 72 h post-treatment we analyzed cell signaling pathways known to be upregulated in ER+ breast cancer via immunoblotting." (PMID 37443749, 2023). "Given that the oncogenic functions of NRP2 activate many signaling pathways by binding with SEMA3C, we investigated the role of miR-146a (a regulator of NRP2 expression) in breast cancer aggressiveness." (PMID 33396906, 2020). "Zhu and coauthors demonstrated that the knockdown of SEMA3C significantly inhibited breast cancer cell MCF-7 growth and migration; therefore, it would be interesting to examine how the Sema3C R745A mutant affects the endothelial cell migration process." (PMID 30304095, 2018). "To investigate whether SEMA3C activates these pathways in ER+ breast cancer cells, we treated MCF7 and T47D cells with recombinant SEMA3C in a dose-dependent manner." (PMID 37443749, 2023). "Importantly, we demonstrate that silencing SEMA3C inhibits the MAPK and AKT signaling pathways, promotes apoptosis, and suppresses the growth of both tamoxifen-sensitive and resistant ER+ breast cancer cells." (PMID 37443749, 2023). "To investigate SEMA3C’s potential role as a driver of breast cancer, we needed to induce SEMA3C signaling via the stimulation of ER+ breast cancer cells and examine whether SEMA3C can activate RTK signaling pathways that are commonly observed in breast cancer." (PMID 37443749, 2023).
glioma (20 papers, 2008 to 2024). A benign or malignant brain and spinal cord tumor that arises from glial cells (astrocytes, oligodendrocytes, ependymal cells). "While most of the associations between SEMA3C and brain malignancies has been identified in gliomas, SEMA3C has also been implicated in neuroblastoma." (PMID 30759745, 2019). "In this study, we aimed to elucidate role of Sema3C in glioma associated angiogenesis process by applying the Sema3C-overexpressing derivative of the glioblastoma cell line U87 MG on a CAM model." (PMID 31726800, 2019). "Mouse genetics and other studies have found that Plexins A1, A2, and D1 in association with Nrp1 and Nrp2 are receptors for SEMA3C in endothelial cell and glioma stem cells." (PMID 29348142, 2018). "The results showed that high levels of Sema3C protein in glioma samples was markedly associated with a shorter overall survival (p < 0.0001)." (PMID 26032848, 2015). "Regarding Sema3C association with glioma, relatively high mRNA levels of Sema3C have been detected in a number of glioma cell lines and also in short-term glioma cultures derived from surgically removed tumor tissue." (PMID 26032848, 2015). "Findings presented in our study show that the increased protein level of Sema3C is associated with the progression of glioma malignancy and poor patient survival." (PMID 26032848, 2015). "Sema3C upregulation was distinctly associated with the poor prognosis in glioma patients, especially with high WHO grade." (PMID 26032848, 2015). "The Kaplan–Meier analysis using the log-rank test was performed to determine the association of Sema3C expression with clinical outcome of glioma patients." (PMID 26032848, 2015). "In this study, we investigated how expression levels of Sema3C in post-operative glioma tumors are associated with the malignancy grade and the survival of the patient." (PMID 26032848, 2015). "In gliomas, SEMA3C expression is closely linked to their severity." (PMID 38321460, 2024). "By using immunoblot analysis (Western blot), we aimed to test whether expression of Sema3C at the protein level is associated with the different histopathological grades of glioma." (PMID 26032848, 2015). "In this study, we evaluated the Sema3C expression in different grade glioma tissues to test our hypothesis that Sema3C might be associated with the malignancy of this type of tumor and patient outcome." (PMID 26032848, 2015). "The data presented in this work suggest that the increased levels of Sema3C protein may be associated with the progression of glioma tumor and has a potential as a prognostic marker for outcome of glioma patients." (PMID 26032848, 2015). "Similarly, the Univariate Cox regression analysis also indicated that clinical variables including age (p < 0.0001), pathological grade (I-II vs. III-IV WHO grade gliomas; p < 0.0001), and Sema3C protein levels (p = 0.0001) were significantly associated with the overall survival." (PMID 26032848, 2015). "SEMA3C is closely related to glioma progression, and several studies have demonstrated that its high expression promotes glioma malignancy and is indicative of a poor prognosis." (PMID 38584840, 2024). "Previous work suggested that semaphorin 3C, plexin A2, plexin D1, and Nrp1 form a complex in glioma stem cells, whereas numerous studies have indicated the interaction of semaphorin 3A, plexins, and Nrp1." (PMID 34270956, 2021). "For example, miR-142-5p inhibits the proliferation and invasion of glioma cells by targeting Sema3C." (PMID 33509213, 2021). "Knockdown of SEMA3C was able to reduce sphere formation and inhibit proliferation of glioma stem cells as well as impair tumor formation in intracranial xenografted glioma stem cells in mice." (PMID 30759745, 2019). "For example, SEMA3C mediates signalling via Plexin B1 in PCa whereas SEMA3C signals through Plexin D1 in glioma." (PMID 30759745, 2019).